RNF13 (ring finger protein 13)
Description:
E3 ubiquitin-protein ligase that regulates cell proliferation. Involved in apoptosis regulation. Mediates ER stress-induced activation of JNK signaling pathway and apoptosis by promoting ERN1 activation and splicing of XBP1 mRNA. Also involved in protein trafficking and localization.
Synonyms: RZF; DEE73; EIEE73
Tractability: Antibody: UniProt predicts a signal peptide or a membrane-spanning region. PROTAC: UniProt records ubiquitination sites on it; ubiquitination databases record sites on it; its protein half-life has been measured.
Gene: Protein-coding gene on chromosome 3 (149,809,445 to 149,962,153, forward strand). Ensembl gene ENSG00000082996.
Subcellular location: Endoplasmic reticulum membrane; Late endosome membrane; Lysosome membrane; Nucleus inner membrane
Subcellular location (Human Protein Atlas): Nucleoplasm; Vesicles; Cytosol
Gene Ontology:
Molecular function: JUN kinase binding; protein binding; ubiquitin protein ligase activity; ubiquitin-protein transferase activity
Biological process: organelle localization; positive regulation of JNK cascade; protein autoubiquitination; ubiquitin-dependent protein catabolic process; protein ubiquitination
Cellular component: endoplasmic reticulum; endoplasmic reticulum membrane; endosome; lysosomal membrane; late endosome membrane; nuclear inner membrane
Genetic constraint (gnomAD): Loss-of-function variants: 3 observed, 9.54 expected, observed/expected ratio (o/e) 0.31, 90% interval 0.14 to 0.81. That is too few expected variants to judge how well the gene tolerates losing a copy. Missense variants: 148 observed, 171.33 expected, observed/expected ratio (o/e) 0.86, 90% interval 0.75 to 0.99. Synonymous variants: 55 observed, 63.49 expected, observed/expected ratio (o/e) 0.87, 90% interval 0.7 to 1.08.
Homologues: Orthologues: chimpanzee RNF13 (100% identical), macaque RNF13 (99% identical), dog RNF13 (98% identical), pig RNF13 (98% identical), mouse Rnf13 (93% identical), rat Rnf13 (93% identical), rabbit RNF13 (88% identical), guinea pig RNF13 (86% identical), zebrafish rnf13 (76% identical), tropical clawed frog rnf13 (72% identical). Paralogues in human: RNF167 (44% identical), ZNRF4 (33% identical), RNF130 (23% identical), RNF150 (23% identical), RNF128 (22% identical), RNF133 (20% identical), RNF149 (20% identical), RNF148 (17% identical), RNF215 (12% identical).